KRAS (KRas proto-oncogene, GTPase)
Diseases named in the same sentence as KRAS in open-access papers (continued):
Sharing a sentence is not in itself a finding about the gene and the disease.
lung cancer (continued). "In a lung cancer mouse model, it has been demonstrated that IL-10 and TGFβ secreted by KRAS mutated cancer cells, induce the conversion of CD4+ CD25- T-cells into FOXP3+/CTLA4+/CD122+ T regulatory cells (Tregs)." (PMID 33777798, 2021). "K-RAS(G12C) mutations only account for a small proportion of KRAS mutations that are found in cancer and are primarily found in lung cancer." (PMID 35582302, 2021). "Analysis of the Pan-Lung Cancer gene set by The Cancer Genome Atlas indicates that STK11 loss is positively correlated to KRAS mutations in adenocarcinoma, whereas loss of PTEN is associated with squamous cell cancers." (PMID 33652656, 2021). "Activated KRAS is associated with lung cancer, and we observed that Kras has a gain-of-function mutation in approximately 25% of the samples." (PMID 33652656, 2021). "The corresponding KRAS variants were directly validated from all lung cancer tissues where a lung biopsy sample was available (cases 4, 6, 8, 9, 10 and 12)." (PMID 34257581, 2021). "KRAS mutations are key oncogenic regulators in the development of many human malignant cancers, including lung cancer." (PMID 34217313, 2021). "Low expression of SDPR was associated with shorter OS in NSCLC patients as well as in KRAS-mutant group, based on GEO dataset and lung cancer microarray (GSE72094, HLugA180Su06, P < 0.05)." (PMID 33435990, 2021). "A549 cells, which present mutation in KRAS and display the Warburg phenotype, are resistant to current lung cancer therapies." (PMID 33806075, 2021). "The KRAS pathway is activated in both models, either by an activating mutation in the A/J lung cancer model or by activation of upstream signaling pathways in the MMTV-Neu model of HER2-positive breast cancer." (PMID 34638488, 2021). "For this, we used the CCLE mutation dataset as well as the Achilles dataset of genome-wide CRISPR knockout screens to map known driver mutations in lung cancer (e.g. KRAS, EGFR, PI3KCA) and the genes identified as essential for proliferation." (PMID 34911571, 2021). "KRAS is the second most common driver gene in lung cancer, and the frequency of KRAS mutation is lower in Chinese patients than in Western populations." (PMID 33928034, 2021). "Lung cancer, which accounts for the most cancer deaths worldwide, harbours KRAS mutations in approximately 25% of cases with variation by histology and patient demographic." (PMID 34200676, 2021). "We used the Pan-Lung Cancer (TCGA, Nat Genet 2016, n = 1144) database to analyze the specificity of KRAS mutation and BLT2." (PMID 34635780, 2021). "KRAS is another important oncogenic driver in lung cancer, with KRAS mutations accounting for approximately ~15–30% of NSCLC cases." (PMID 34068816, 2021). "Activation of the kinase AXL induces EGFR-TKI resistance associated with the mesenchymal phenotype, and the dual blockade of MEK and AXL overcomes EMT-mediated drug resistance and synergistically suppresses tumor growth in KRAS-mutated lung cancer cells." (PMID 34885068, 2021). "KRAS-mutant lung cancers are often smoking-associated and have high tumour mutational burden and PD-L1 expression." (PMID 34200676, 2021). "KRAS is one of the most commonly mutated oncogenes in lung cancer but has long been considered undruggable." (PMID 35602221, 2021). "FGFR1 was found to mediate acquired resistance to trametinib in a panel of KRAS-mutated lung cancer cell lines in a shRNA screen targeting the human kinome." (PMID 34068816, 2021). "Of course, further experiments with more KRAS mutant lung cancer patient samples are needed to demonstrate the linkage between BLT2 expression and KRAS mutation in human lung cancer." (PMID 34635780, 2021). "For example, in lung cancer, the commonest KRAS G12 mutation is G12C, possibly associated with tobacco smoke exposure, while in colon and pancreas cancers, G12D is the commonest." (PMID 34200676, 2021).
lung cancer (continued). "Oncogenic KRAS mutations combined with the loss of the LKB1 tumor-suppressor gene (KL) are strongly associated with aggressive forms of lung cancer." (PMID 34016959, 2021). "EGFR and KRAS mutation characteristics in patients with lung cancer from Xuanwei/Qujing in previous studies." (PMID 33928034, 2021). "Smoking status was long ago found to correlate with certain oncogene mutations in lung cancer, with mutation of oncogenes such as KRAS commonly found in smokers." (PMID 34497760, 2021). "We identified a tumor-specific, mutant-KRAS-associated subpopulation which is conserved in both human and murine lung cancer." (PMID 33854168, 2021). "For unclear reasons, mutations in KRAS are more common in pancreatic (80%–90%), colorectal (40%–60%), and lung cancers (30%); in contrast, mutations are rarely found in breast (1%–2%) and head and neck cancers (1%)." (PMID 35141142, 2021). "ASOs targeting ARL4C (ASO-1316) showed decreased RAS-related substrate activity, inhibited cell proliferation and migration, and suppressed nuclear import of Yes-associated protein-1 (YAP-1) in lung cancer cell lines bearing KRAS and EGFR mutations." (PMID 33740988, 2021). "In this present work, we have highlighted an induced overexpressed SOX2‐OT level, where siRNAs knockdown of SOX2‐OT reduces total‐ and phosphorylated‐AKT protein levels in EGFR‐wild‐type, KRAS‐mutated A549 lung cancer cells." (PMID 33433063, 2021). "Due to mutations in EGFR and KRAS appearing to be mutually exclusive in lung cancer patients, the results are especially worth noticing." (PMID 33725808, 2021). "Several studies have shown that mutations in KRAS play a critical role in metabolic reprogramming in multiple cancers, including lung cancer." (PMID 33806075, 2021). "In particular, epigenetic modification concur to lung cancer spreading and some data available have shown that there is an interaction between KRAS mutations and epigenetic changes." (PMID 35004317, 2021). "When taking KRAS mutation as one of the earliest discoveries of genetic alterations in lung cancers and reported as very important for tumor progression into account, there seemed to bear discrepancy at different stages of tumor progression." (PMID 34589430, 2021). "This study aimed to develop CRISPR–Cas12a as a test to sensitively detect KRAS mutations in lung cancer." (PMID 33467412, 2021). "According to the literatures, KRAS mutations are common in pancreas, colon and lung cancers, whereas NRAS mutations are common in myeloid leukemias and cutaneous melanomas." (PMID 34102999, 2021). "RAS gain-of-function mutations are present in ~30% of all human cancers, with KRAS being the most frequently mutated isoform showing alterations in different cancer types including lung cancer." (PMID 34684076, 2021). "The transforming function of mutant RAS was first described by Mariano Barbacid and colleagues in 1982, and the case of a lung cancer patient with an activating KRAS mutation was published only two years later." (PMID 33809660, 2021). "Of note, in the last couple of years, different compounds have been proposed as inhibitors of KRAS G12C mutation in colorectal and lung cancers." (PMID 34440587, 2021). "Murine models of lung carcinoma harbouring oncogenic KRAS mutations exhibited enhanced proliferation and immunosuppressive IL-6 production by myeloid cells within the TME." (PMID 34944851, 2021). "The therapeutic inhibition of IL-6 in KRAS-mutated murine models of lung cancer reduced tumour progression and featured a decrease in tolerogenic macrophages, MDSCs and Tregs." (PMID 34944851, 2021).
lung cancer (continued). "KRAS is of tremendous interest in oncology because KRAS mutations occur in 22% of all tumours, including 61% of pancreas, 33% of colon and 17% of lung cancers, 3 of the 5 most lethal cancers world-wide." (PMID 32326637, 2020). "The KRAS G12 variants are among the most frequent mutations found in human gastrointestinal and lung cancers." (PMID 33298945, 2020). "More recently, the data have also shown that loss of function of KEAP1 promotes KRAS-driven lung cancer and results in the dependence on glutaminolysis." (PMID 32576270, 2020). "While direct KRAS G12C inhibitors have shown promising results in some solid tumors including LADC, the development of new potential therapeutic strategies for the treatment of KRAS-mutated lung cancer is a work in progress, and many questions remain." (PMID 32548736, 2020). "Recently, attention has also been drawn to the special histology and co-occurring mutations in KRAS-mutant lung cancer." (PMID 32548736, 2020). "KRAS-mutated lung cancer presents distinct immune profiles, biology, and therapeutic vulnerabilities in different subsets classified by co-occurring genetic events." (PMID 33194652, 2020). "EGFR and KRAS are the most frequently mutated genes in lung cancer, being active research topics in targeted therapy." (PMID 32107398, 2020). "KRAS mutation plays a critical role in the initiation and development of non‐small cell lung cancer (NSCLC)." (PMID 31709742, 2020). "So far, only 17 patients were treated on maximum tolerated dose and only 13 patients had KRAS mutated lung cancer." (PMID 32436621, 2020). "We intend to provide a valuable reference for pharmacological evaluation and rational clinical drug use in patients with KRAS mutated lung cancer." (PMID 33240601, 2020). "KRAS mutations occur in approximately 30% of all human cancers, notably occurring in the most lethal cancers such as pancreatic cancer, colon cancer and lung cancer." (PMID 32244355, 2020). "KRAS mutation is the second most prevalent mutation in lung cancer, and we observed that KRAS regulated the mRNA of ACAA1." (PMID 33194642, 2020). "It is of note that in experimental lung cancer models, a similar association between G12D mutation of KRAS with genomic instability was observed." (PMID 32725342, 2020). "KRAS is one of the most common driver mutations in human lung cancer and correlates with aggressive disease progression and poor patient prognosis." (PMID 33335263, 2020). "For example, it was recently shown that TRAIL/TRAILR2 signaling increases migration and invasion via a Rac1/PI3K signaling axis in KRAS mutated nonsmall-cell lung cancer and pancreatic ductal adenocarcinomas." (PMID 32433558, 2020). "The lung cancer patients with different KRAS mutations display distinct sensitivity to chemotherapy and targeted therapy." (PMID 32244355, 2020). "It has to be noted here that the metabolic alterations supported by KRAS mutations depend on the tissue context, for example KRAS-driven lung cancer displayed increased BCAA metabolism, being the opposite in PDAC." (PMID 32756381, 2020). "On the contrary, cluster 2 of KRAS mutant lung cancer was characterized by the highest mutation burden, an active immunoediting and high PDL1 expression." (PMID 32725342, 2020). "Inhibition of the MAPK pathway alone is insufficient to cure KRAS-mutant lung cancer because, as a monotherapy, it causes drug resistance through enhanced AKT signaling." (PMID 32728173, 2020). "More specifically, predictive models for EGFR and KRAS mutation status in lung cancer were developed." (PMID 32107398, 2020). "Using genetically engineered mouse models, the authors show that loss of REDD1 promotes the development of oncogenic KRAS-driven pancreatic and lung cancers." (PMID 32273287, 2020). "In the last decade, researchers have uncovered the source of one of the important mutations is called as Kirsten rat sarcoma oncogene (KRAS) mutations in lung cancers using molecular studies." (PMID 32117436, 2020).
lung cancer (continued). "Here, we explored the underlying mechanisms of action of PIERCE1 in KRAS-mutant lung cancer, which accounts for 30% of all lung adenocarcinoma cases." (PMID 32728173, 2020). "Kirsten rat sarcoma oncogene (KRAS) mutations have been considered as a key driver for lung cancers." (PMID 32117436, 2020). "KEY POINTS: To the best of our knowledge, this is the first case of multiple primary lung cancers harboring distinct KRAS mutations." (PMID 32415761, 2020). "These outstanding results are further signified by the fact that KRAS mutations are linked with resistant lung cancer and poor prognosis in patients." (PMID 32429547, 2020). "Malignancies from endodermal tissues frequently harbor KRAS mutations, and GATA6 expression correlates with KRAS mutations in human lung cancers." (PMID 32157212, 2020). "Among cancers with the highest mortality rates, KRAS-activating mutations occur in ~ 90% of pancreatic cancers, 40% of colon cancers and 30% of lung cancers." (PMID 33060649, 2020). "In lung cancer, oncogenic KRAS restrictedly expressed in lung epithelial cells causes an accumulation of Th17 cells in tumour tissues." (PMID 33116132, 2020). "The inactivation of KEAP1 in KRAS mutations is related to the inhibition of glutaminase in lung cancer." (PMID 32206449, 2020). "Here, using an established tumoursphere formation assay to enrich for lung TICs, we show that IKKβ is critical to sustain stemness-associated features in KRAS-driven lung cancer cells." (PMID 32823550, 2020). "Further, mutations in the KRAS gene, which are acquired mutations, closely mimic the events that lead to spontaneous lung cancer development in humans." (PMID 32770960, 2020). "KRAS is the most frequently mutated isoform in lung cancer representing 19% of the cases, followed by NRAS (1%) and HRAS (< 1%)." (PMID 32962236, 2020). "Induction of Rac1b expression in lung cancer cells leads to a bypass of KRAS-associated senescence and up-regulates expression of metalloproteases MMP-3 and MMP-9." (PMID 32158759, 2020). "The necessity of other RAS mutant inhibitor raises that while KRAS-G12C mutation occurs most frequently in lung cancers, in the most commonly RAS mutated pancreatic and colon cancers." (PMID 32770300, 2020). "One of the most commonly mutated genes in lung cancer is the Kirsten rat sarcoma viral oncogene homolog (KRAS), which is mutated in around 30% of all lung adenocarcinomas." (PMID 33322500, 2020). "Consistent with this concept, anti-inflammatory therapy with the IL-1β monoclonal antibody canakinumab in NSCLC, which is often driven by KRAS mutations, significantly reduced lung cancer incidence and mortality." (PMID 33116132, 2020). "For example, non–small cell lung cancer genotyping requires mutation pattern analysis of KRAS, EGFR, and BRAF." (PMID 32329738, 2020). "The chemoresistance observed in lung cancer patients harboring KRAS oncogenic mutations was suggested to be the consequence of KRAS mediated upregulation of NRF2 transcription factor, an oncogenic hub of oxidative stress response." (PMID 32545208, 2020). "Among lung cancer patients, KRAS mutation is the commonest mutation and 27% of LUAD patients harbor it." (PMID 33072585, 2020). "We found KRAS mutations in three of the examined patients, which likely represented different tumor clones, indicative of the heterogenous nature of lung cancer." (PMID 32290439, 2020). "KRAS oncogenic mutations are widespread in lung cancer and, because direct targeting of KRAS has proven to be challenging, KRAS-driven cancers lack effective therapies." (PMID 32823550, 2020). "On the other hand, analysis of asbestos-induced lung cancers demonstrated that although KRAS mutation rate is significantly high but it is related to the smoking-induced mutations, not the asbestos effects." (PMID 32725342, 2020). "In a transgenic mouse model of KRAS-induced lung cancer, invasive adenocarcinoma is modeled by the loss of the TGF-β receptors." (PMID 33537237, 2020).
lung cancer (continued). "The most common genetic alterations found in lung cancer patients include activating-point mutations in KRAS, which are present in a third of lung adenocarcinoma patients, and are causally correlated with poor prognosis." (PMID 32823550, 2020). "Different from other lung tumor animal models, our model limits the insult to the lung, and mutations in the KRAS gene are acquired mutations, closely mimicking the events that lead to lung cancer development in human patients." (PMID 32770960, 2020). "Instead of copy-number amplification, KRAS is frequently mutated in a wide array of tumors including lung cancer and pancreatic cancer." (PMID 32405341, 2020). "Another possible application is in KRAS-mutated lung cancer, where loss of the Lkb1 tumor suppressor activates Src signaling." (PMID 32509799, 2020). "Targeting lonidamine to mitochondria can inhibit AKT/mTOR signal, induce autophagic death of lung cancer cells with KRAS mutation and block tumorigenesis and brain metastasis." (PMID 33537237, 2020). "Previous studies in lung cancer suggested that KRAS mutation is a poor prognostic marker for response to EGFR TKI treatment." (PMID 32505185, 2020). "Among the RAS gene family, KRAS is the most commonly mutated, which occurs in 71% of pancreatic, 29% of colorectal, and 18.6% of lung carcinomas." (PMID 33122197, 2020). "In analogy with KRAS-driven pancreatic cancer cells, KRAS-mutated lung cancer cells also exhibit constitutive macropinocytosis." (PMID 31803611, 2019). "To investigate the mechanism underlying the effects of combined AZ628 and BP-1-102 on KRAS mutant lung cancer cells, we evaluated the role of these inhibitors in MEK/ERK signaling pathway." (PMID 31484165, 2019). "The identification of dependencies borne through common co-occurring mutations are sought to more effectively target KRAS-mutant lung cancer." (PMID 31519898, 2019). "Meanwhile, in lung cancer, the majority of reports associate mutant KRAS with increased PD-L1 expression and improved clinical response to anti-PD-1 therapy." (PMID 31847096, 2019). "In an internal review of collective Target Selector results of patients with lung cancer, slightly over 20% had KRAS exon 2 mutations and more than 20% showed activating mutations, whereas only 1.69% of patients had BRAF mutations." (PMID 31581267, 2019). "Our results confirm previous studies showing that EGFR mutations are more prevalent than KRAS in Chinese lung cancer patients, in contrast to previously reported Caucasian populations." (PMID 31369215, 2019). "Lung adenocarcinomas (LUADs) with somatic mutations in the KRAS oncogene comprise the most common molecular subtype of lung cancer in smokers and present with overall dismal prognosis and resistance to most therapies." (PMID 31001473, 2019). "We believe that our study will help researchers further understand the roles of the KRAS gene and its encoded protein in lung cancer, which will provide guidance for future experimental study." (PMID 31117243, 2019). "The development of this KRAS agonist as a new class of anticancer drug offers a potentially effective strategy for the treatment of lung cancer with KRAS mutation and/or mutant KRAS-driven lung cancer." (PMID 30971271, 2019). "In lung cancer, so far only two studies have addressed the impact of KRAS mutation on the efficacy of BEV." (PMID 31600989, 2019). "This SNP was associated with increased expression of KRAS, reduced expression of let-7 and increased risk of lung cancer." (PMID 30860980, 2019). "The first evidence showing RKIP as a modulator of cell signaling in lung cancer came from in vitro experiments using a KRAS adenocarcinoma mutated cell line (A549)." (PMID 31083461, 2019). "The major clinical problem is KRAS, which is mutated in >90% of pancreatic cancers, ∼50% of colon cancers, and ∼25% of non–small cell lung cancer." (PMID 31451509, 2019).